PHOSPHO1 (phosphoethanolamine/phosphocholine phosphatase 1)
Diseases named in the same sentence as PHOSPHO1 in open-access papers:
PHOSPHO1 is named in the same sentence as 36 diseases in open-access papers, as found by Europe PMC text mining. Sharing a sentence is not in itself a finding about the gene and the disease. The quoted sentences say what the papers report.
type 2 diabetes (8 papers, 2018 to 2022). "A previous study found that DNA methylation at the PHOSPHO1 was associated with type 2 diabetes and positively correlated with high density lipoprotein levels." (PMID 29868124, 2018). "Also, it has been proved that DNA methylation at PHOSPHO1 in blood associated with type 2 diabetes risk." (PMID 33539483, 2021). "Increased PHOSPHO1-imputed expression was associated with higher insulin levels; previous literature reports that decreased methylation status in the body of these gene increases risk of developing type 2 diabetes." (PMID 30624610, 2019). "A nested case-control study including 25,372 individuals identified five loci that were associated with future type 2 diabetes incidence, including ABCG1, PHOSPHO1, SOCS3, SREBF1, and TXNIP." (PMID 35399937, 2022). "Epigenomic association studies indicated that the methylation levels of PHOSPHO1 in whole blood of subjects were positively correlated with their HDL cholesterol levels and negatively correlated with the future risk of developing type II diabetes (T2D)." (PMID 35957983, 2022). "The authors estimated that 32% of the unexplained risk for future type 2 diabetes among Indian Asians compared with controls was associated with a higher methylation score based on the top five markers at TXNIP, ABCG1, SREBF1, SOCS3 and PHOSPHO1." (PMID 29164275, 2018). "To date, only one longitudinal EWAS study focusing on type 2 diabetes has been published, identifying five CpGs associated with disease onset in Indian Asians during the follow-up period, two of which (the CpGs in ABCG1 and PHOSPHO1) were replicated in a prospective study." (PMID 29164275, 2018).
osteomalacia (7 papers, 2011 to 2023). Disorder caused by an interruption of the mineralization of organic bone matrix leading to bone softening, bone pain, and weakness. "PHOSPHO1 deficiency leads to early‐onset scoliosis, osteomalacia, and fractures that mimic pseudo‐HPP." (PMID 36699639, 2023). "PHOSPHO1 initiates bone matrix mineralisation, and PHOSPHO1 deficiency causes significant skeletal pathology, bowed long bones, osteomalacia and scoliosis in early life." (PMID 33092598, 2020). "More recently, PHOSPHO1 deficient mice, Phospho1-R74X (Phospho1 KO) were found to show elevated ePPi levels and to display multiple skeletal abnormalities, including spontaneous fractures, bowed long bones, osteomalacia and scoliosis in early life." (PMID 26232374, 2015). "Mice with a Phospho1 gene ablation (Phospho1−/−) live to adulthood but develop scoliosis starting from birth, osteomalacia, greenstick fractures, accompanied by the elevation in plasma PPi and a decrease in plasma TNAP activity." (PMID 36185572, 2022). "Recent studies have found that Phospho1 KO mice (Phospho1-R74X) display multiple skeletal abnormalities with spontaneous fractures, bowed long bones, osteomalacia and scoliosis." (PMID 26232374, 2015). "Phospho1−/− mice display growth plate abnormalities, spontaneous fractures, bowed long bones, osteomalacia, and scoliosis in early life." (PMID 20684022, 2011). "Von Kossa/van Gieson staining revealed characteristics of osteomalacia in Phospho1−/− mice: widespread excessive osteoid (OV/BV = 3.96% in Phospho1−/− mice versus 0.06% in WT mice, p = .0001) and increased width of osteoid at the surfaces of both trabecular and cortical bone." (PMID 20684022, 2011). "Lack of PHOSPHO1 caused a decrease in growth rate, endochondral growth plate, and skeletal abnormalities that included decrease or loss of secondary ossification centers, decreased bone mineral density, spontaneous fractures, osteomalacia, and scoliosis." (PMID 20684022, 2011).
diabetes (6 papers, 2019 to 2025). "Osteoblasts isolated from Phospho1−/− mice were enriched for genes associated with energy metabolism and diabetes; Phospho1 both directly and indirectly interacted with genes associated with glucose transport and insulin receptor signalling." (PMID 33092598, 2020). "Several previous reports have suggested an association between PHOSPHO1 expression in disorders of altered energy metabolism such as obesity and diabetes." (PMID 33092598, 2020). "Several other studies have found intriguing associations between PHOSPHO1 expression and disorders of altered energy metabolism such as diabetes and obesity." (PMID 31372594, 2019). "Ebselen, another PHOSPHO1 inhibitor, could improve insulin sensitivity and ameliorate diabetes-associated atherosclerosis in mice." (PMID 35957983, 2022). "Phospho1 deficiency results in decreased blood glucose levels, improved insulin sensitivity, glucose tolerance and conferred protection from diet-induced obesity and diabetes in mice despite a 60-fold upregulation of Esp expression by Phospho1−/− osteoblasts." (PMID 33092598, 2020). "Phospho1−/− mice, which lack PHOSPHO1, have been shown to have improved glucose homeostasis compared to their wild type (WT) littermates, and resist high-fat-diet-induced weight gain and diabetes." (PMID 40470038, 2025). "This study identifies PHOSPHO1 as a potential bone-derived therapeutic target for the treatment of obesity and diabetes." (PMID 33092598, 2020). "Studying how metabolic networks are affected by PHOSPHO1 inhibition—particularly when comparing healthy patients to those with diabetes or obesity—could affect disease understanding, diagnosis, and treatment methods." (PMID 40470038, 2025). "PHOSPHO1 transcript was increased in the liver of nonalcoholic steatohepatitis patients and diminished in the liver of hepatitis mice, myocardial tissue of mice with left ventricular hypertrophy, and muscle of mice with type 1 diabetes mellitus." (PMID 35957983, 2022). "Moreover, due to its role in arterial wall mineralization, PHOSPHO1, can be considered as a therapeutic target for cardiovascular disorders, obesity and diabetes." (PMID 35655232, 2022). "We show that mice lacking the bone mineralisation enzyme PHOSPHO1 exhibit improved basal glucose homeostasis and resist high-fat-diet-induced weight gain and diabetes." (PMID 33092598, 2020). "Mice lacking PHOSPHO1 showed improved basal glucose homeostasis and were protected from HFD-induced obesity and diabetes, which was independent of altered bone secreted factors." (PMID 35957983, 2022).
scoliosis (6 papers, 2011 to 2023). A congenital or acquired spinal deformity characterized by lateral curvature of the spine. "In addition, this treatment corrected congenital scoliosis in the model of pseudo‐HPP caused by Phospho1 gene deletion." (PMID 36699639, 2023). "Multiple fractures were seen from postnatal day 1, and prominent scoliosis was observed already on postnatal day 10 in [Phospho1−/−; Akp2+/−] mice compared with 1 month of age in Phospho1−/− mice." (PMID 20684022, 2011). "The present data, treating mice with a Phospho1‐deficient pseudo‐HPP phenotype, show efficacy in the skeletal manifestations (complete prevention of scoliosis and improvement in the trabecular architecture), while there were no dentoalveolar deficits before or after treatment." (PMID 36699639, 2023). "Here we show that, indeed, the use of AAV8‐TNAP‐D10 prevents severe scoliosis that characterizes this murine model with improvements in the trabecular bone and a reduced marrow space in the vertebrae of AAV8‐TNAP‐D10‐treated Phospho1−/− mice." (PMID 36699639, 2023).
Obesity (5 papers, 2019 to 2025). Accumulation of substantial excess body fat. "Another study revealed that PHOSPHO1 was a regulator of insulin resistance and obesity." (PMID 35957983, 2022). "At the same time, it is also necessary to carefully evaluate the effect and mechanism of PHOSPHO1 inhibitors on energy metabolism to provide novel strategies for the prevention and treatment of chronic metabolic disorders that plague human beings in the era of the obesity pandemic." (PMID 35957983, 2022). "Consequently, inhibition of PHOSPHO1 activity could potentially treat obesity and related metabolic disorders." (PMID 35957983, 2022). "In addition, depletion of the PHOSPHO1 gene ameliorated HFD-induced obesity, MAFLD, and insulin resistance in mice, indicating that PHOSPHO1 negatively regulates BAT activation and energy metabolism." (PMID 35957983, 2022). "Supporting this idea, changes in Phospho1 expression have been found in several studies examining the thermogenic brown adipose tissue (BAT) and the browning of white adipose tissue (WAT), of great relevance to obesity." (PMID 31372594, 2019). "Levels of high molecular weight adiponectin, a hormone linked to insulin-sensitisation, were decreased in Phospho1−/− mice fed either a CD (2.62-fold) or a HFD (1.92-fold) (both p < 0.001) suggesting that insulin sensitivity and protection from obesity are independent of adiponectin." (PMID 33092598, 2020).
Insulin resistance (3 papers, 2020 to 2022). Increased resistance towards insulin, that is, diminished effectiveness of insulin in reducing blood glucose levels. "These markers located in ABCG1, PHOSPHO1, SOCS3, SREBF1, and TXNIP were associated with metabolic measures of insulin resistance including glucose concentration, BMI, waist-to-hip ratio, and homeostatic model assessment for insulin resistance (HOMA-IR)." (PMID 32211026, 2020). "Based on the inhibition of PHOSPHO1 activity by proton pump inhibitors and the effect of PHOSPHO1 deletion on glucose tolerance and insulin resistance, PHOSPHO1 may be involved in proton pump inhibitors-regulated metabolic homeostasis, which requires further experimental validation in the future." (PMID 35957983, 2022).
hyperparathyroidism (2 papers, 2019 to 2022). Hyperfunction of the parathyroid glands resulting in the overproduction of parathyroid hormone. "The in vitro data suggest that the TNAP reduction in CKD-MBD is driven by the hyperphosphatemia and/or hyperparathyroidism noted in these mice, while the higher PHOSPHO1 expression may be a compensatory mechanism." (PMID 35900032, 2022).
osteosarcoma (2 papers, 2019 to 2022). A usually aggressive malignant bone-forming mesenchymal neoplasm, predominantly affecting adolescents and young adults. "PHOSPHO1 is specifically expressed in bone lesions, and NFATC1 is associated with normal osteocyte function and osteosarcoma pathogenesis." (PMID 36619306, 2022).
atherosclerosis (1 paper, 2021). A disease characterized by the build-up of fatty material and calcium deposition in the arterial wall resulting in partial or complete occlusion of the arterial lumen. "PHOSPHO1 up-regulated express in rabbit models with hyperlipidemia and atherosclerosis." (PMID 33539483, 2021).
dyspepsia (1 paper, 2020). An uncomfortable, often painful feeling in the stomach, resulting from impaired digestion. "Also, inhibitors of PHOSPHO1 activity such as the proton pump inhibitor lansoprazole, commonly prescribed to control and prevent symptoms of gastroesophageal reflux disease and dyspepsia, have been associated with improved glycaemic control in diabetic patients." (PMID 33092598, 2020).
energy metabolism disorders (1 paper, 2022). "PHOSPHO1 that encodes the bone-specific phosphatase involves in energy metabolism disorders." (PMID 35655232, 2022).
epilepsy (1 paper, 2025). A brain disorder characterized by episodes of abnormally increased neuronal discharge resulting in transient episodes of sensory or motor neurological dysfunction, or psychic dysfunction. "We analyzed OLINK proteomics data from a large epilepsy cohort in which we have previously found four differentially expressed proteins (CDH15, PAEP, LTBP3, PHOSPHO1)." (PMID 40591616, 2025).
hypophosphatasia (1 paper, 2025). Hypophosphatasia (HPP) is a rare heritable metabolic disorder characterized by defective mineralization of bone and/or teeth in the presence of reduced activity of unfractionated serum alkaline phosphatase (ALP). "Furthermore, the defective skeletal and dental mineralisation in patients with hereditary hypophosphatasia and the atypical femur fractures noted in humans with PHOSPHO1 mutations phenocopy the skeletal defects reported in Alpl and Phospho1 deficient mice." (PMID 40791815, 2025).
metabolic syndrome (1 paper, 2023). A cluster of metabolic risk factors for CARDIOVASCULAR DISEASES and TYPE 2 DIABETES MELLITUS. "Parallel studies have further revealed a novel role for PHOSPHO1 as a negative regulator of brown adipose tissue thermogenesis, and have identified the inhibition of PHOSPHO1 or enhancement of the PHOSPHO1 substrate phosphocholine as innovative approaches to manage the metabolic syndrome." (PMID 39184263, 2023).
renal fibrosis (1 paper, 2022). A final common manifestation of a wide variety of chronic kidney diseases characterized by glomerulosclerosis and tubulointerstitial fibrosis. "To answer this, we completed a full renal histopathological examination of the kidneys and renal scoring of tubular atrophy, protein casts, interstitial inflammation, and renal fibrosis of sections in the WT CKD mice and PHOSPHO1 KO CKD mice were similar (data not shown)." (PMID 35900032, 2022).
sarcoma (1 paper, 2022). A usually aggressive malignant neoplasm of the soft tissue or bone. "Some characteristically methylated genes are associated with bone lesions or osteocyte activity, but detailed investigation of their relationship with sarcoma is still lacking, for example, PHOSPHO1 and NFATC1." (PMID 36619306, 2022).
Stillbirth (1 paper, 2011). Death of the fetus in utero after at least 22 weeks of gestation. "Of 272 pups born to Phospho1+/− × Akp2+/− and [Phospho1−/−; Akp2+/−] × [Phospho1−/−; Akp2+/−] matings, only one double-knockout [Phospho1−/−; Akp2−/−] pup was born, and that was a stillbirth." (PMID 20684022, 2011).
tricho‐rhino‐phalangeal syndrome (1 paper, 2023). "Mutations in the Trps1 gene lead to the human condition tricho‐rhino‐phalangeal syndrome which is characterised by craniofacial and skeletal dysplasias and siRNA mediated knockdown of Trps1 in a pre‐odontoblastic cell line leads to the suppression of Phospho1, Alpl and Smpd3 expression." (PMID 36540015, 2023).
cancer (2 papers, 2024 to 2025). A tumor composed of atypical neoplastic, often pleomorphic cells that invade other tissues. "Some of these genes are involved in metabolic pathways including fatty acid beta-oxidation and calcification (CPT1A and PHOSPHO1) and in some cancers (PRMT1)." (PMID 37793095, 2024). "In addition, PHOSPHO1 may also be used as a target for treatment of cancers." (PMID 40396905, 2025).
cardiovascular disease (2 papers, 2022). "Blood eQTL analysis revealed that PHOSPHO1, which generates inorganic Pi and contributes to vascular calcification, was associated with the development of cardiovascular disease." (PMID 35957983, 2022).
metabolic disease (2 papers, 2020 to 2022). A congenital disorder (due to inherited enzyme abnormality) or acquired (due to failure of a metabolically important organ) disorder resulting from an abnormal metabolic process. "Taken together, these findings suggest that in addition to the established role of PHOSPHO1 in biomineralisation of the skeleton and dentition, Phospho1 ablation may result in improved glucose homeostasis and a reduction in metabolic disease susceptibility." (PMID 33092598, 2020). "The phenotypes resulting from overexpression of PHOSPHO1 have not been reported yet, which would be important to complete our understanding of PHOSPHO1’s function in metabolic disorders." (PMID 35957983, 2022). "We review the structure, regulation and role of PHOSPHO1 and its associated phospholipids homeostasis in metabolic disorders and discuss the possibility of targeting PHOSPHO1 and its regulated phospholipids for treating metabolic disorders in mammalian system." (PMID 35957983, 2022). "Accordingly, future functional experiments can be carried out with screened PHOSPHO1 inhibitors to evaluate the safety and effectiveness of PHOSPHO1 inhibitors in treating metabolic disorders." (PMID 35957983, 2022). "Since PHOSPHO1 ablation induced the expression of thermogenic genes and promoted thermogenesis, ablation of PHOSPHO1 could presumably decrease superoxide and OxPL generation, which may reduce the risk of OxPL-associated cardiovascular and other metabolic diseases." (PMID 35957983, 2022). "Based on the role of PHOSPHO1 in regulating energy metabolism, PHOSPHO1 inhibitors could be developed to treat metabolic disorders." (PMID 35957983, 2022). "The expression of PHOSPHO1 was related to metabolic disorders." (PMID 35957983, 2022). "Nonetheless, more evidence is needed to determine whether the altered expression of PHOSPHO1 is directly involved in metabolic disorders or a reflection of the regulatory feedback response." (PMID 35957983, 2022). "We also examine mechanistic evidence of PHOSPHO1- and phospholipid-mediated regulation of mitochondrial and lipid droplets functions in the context of metabolic homeostasis, which could be potentially targeted for treating metabolic disorders." (PMID 35957983, 2022).
tumor (1 paper, 2025). "Given PE's involvement in the synthesis of GPI‐anchored proteins, the increased expression of PHOSPHO1 in tumor cells may reduce GPI‐anchored proteins on the cell membrane, thereby limiting the presence of some tumor antigens on the cell membrane." (PMID 40396905, 2025).
PHOSPHO1 also shares sentences with these, for which no sentence is quoted: Thoracic scoliosis (2 papers); Alzheimer disease (1); Arthritis (1); dementia (1); diffuse large B-cell lymphoma (1); gastroesophageal reflux disease (1); Hyperglycemia (1); hyperlipidemia (1); hyperphosphatemia (1); liver fibrosis (1); osteoarthritis (1); renal osteodystrophy (1); rickets (1); skeletal dysplasia (1).